ENO1 (enolase 1)
Diseases named in the same sentence as ENO1 in open-access papers (continued):
Sharing a sentence is not in itself a finding about the gene and the disease.
hepatocellular carcinoma (47 papers, 2011 to 2026). A malignant tumor that arises from hepatocytes. "Multifactorial Cox regression of 11 prognostic genes resulted in seven independent risk genes affecting the prognosis of patients with hepatocellular carcinoma, namely ENO1, NDRG1, NPM1, H2AX, IL33, MT3 and TXNRD1." (PMID 38097352, 2023). "ENO1 expression has also been associated with tumor de-differentiation and venous invasion in hepatocellular carcinoma." (PMID 34136381, 2021). "High expression of ENO1 increased the risk score and the likelihood of poor prognosis, act as a biomarker in patients with hepatocellular carcinoma, and may be a favorable candidate for targeted treatment." (PMID 38097352, 2023). "Notably, overexpression of ENO1, another enolase isozyme, in hepatocellular carcinoma and head and neck cancer has been associated with poor clinical outcomes." (PMID 22185371, 2011). "Overexpression of ENO1 and empty transfection of hepatoma cells with PP solution reduced the number of invasive cells (P < 0.01)." (PMID 39576845, 2024). "Compared with the paracellular tissues (Normal * group), the expression of ENO1 was increased in the hepatocellular carcinoma samples (Tumor * group)." (PMID 38097352, 2023). "Immunohistochemistry experiment was used to measure the expression of ENO1 in paracellular tissues and hepatocellular carcinoma sample." (PMID 38097352, 2023). "By controlling iron homeostasis, ENO1 promotes the survival of hepatocellular carcinoma (HCC) cells." (PMID 37047306, 2023). "Upregulation of ENO1 (alpha-enolase isoform 1) can result in the promotion of hepatocellular carcinoma through oxidative stress and protein misfolding." (PMID 34771120, 2021). "The silencing of the ENO1 gene by siRNA inhibits the proliferation of hepatocellular carcinoma cells, which followed a shortened S phase and an elongated G2/M phase of the cell cycle." (PMID 32013122, 2020). "It has been shown that in hepatitis B virus-related hepatocellular carcinoma patients, ENO1 expression was enhanced in tumor tissue especially for poorly differentiated hepatocellular carcinoma and closely related to tumor size and vascular involvement." (PMID 29483925, 2018). "In hepatocellular carcinoma, head and neck cancer, gynecological malignancies, ENO1 has been shown to be an oncogenic factor promoting tumor progression." (PMID 25951350, 2015). "The survival rate of cells incubated with the ENO1 inhibitor decreased in a time- and dose-dependent manner compared to that of empty transfected cells without inhibitors (all P < 0.05), implying that ENO1 inhibition can inhibit hepatoma cell proliferation." (PMID 39576845, 2024). "In the present study, SMMC-7721 hepatoma cells were transfected to overexpress ENO1." (PMID 39576845, 2024). "The findings indicate that increased expression of ENO1 in T cells may contribute to T-cell exhaustion and Treg infiltration in hepatocellular carcinoma." (PMID 39457014, 2024). "In addition, exosome-derived ENO1 regulates integrin α6β4 expression and accelerates hepatocellular carcinoma (HCC) growth and metastasis." (PMID 36614179, 2023). "Furthermore, we found that ENO1 expression in the hepatocellular carcinoma samples from patients with poor prognosis (Tumor ** group) was higher than the samples from patients with better prognosis (Tumor * group)." (PMID 38097352, 2023). "Moreover, the reduction in the K281hib level on ENO1 induced by aspirin leads to inhibited ENO1 activity and is critical for attenuating glycolysis and the proliferation of hepatoma cells." (PMID 35428309, 2022). "Moreover, ENO1 can be transferred between neoplastic cells via exosome-mediated crosstalk and exosome-derived ENO1 is essential to promote hepatocellular carcinoma growth, metastasis, and patient deterioration." (PMID 35204345, 2022). "Furthermore, it was found that upregulation of ENO1 was correlated with the progression of neuroblastoma, and hepatocellular carcinoma." (PMID 35130884, 2022).
hepatocellular carcinoma (continued). "For example, ENO1 is a potential biomarker for hepatocellular carcinoma (HCC)." (PMID 31431517, 2019). "In hepatocellular carcinoma (HCC), ENO1 can initiate a metastatic cascade 42 by activating the HGFR/WNT signaling pathway through phosphorylation." (PMID 40303285, 2025). "For instance, exosomal ENO1 transferred between hepatocellular carcinoma (HCC) cells mimics the pro-metastatic effects of endogenous ENO1 overexpression." (PMID 41353343, 2025). "Moreover, PP demonstrated a stronger inhibitory effect on the stable transformation of overexpressing ENO1, which suggests that PP may inhibit the invasion of hepatocellular carcinoma cells by acting on ENO1." (PMID 39576845, 2024). "We examined the expression of ENO1 gene in hepatocellular carcinoma tissues at both transcriptomic levels and showed that ENO1 gene was significantly more highly expressed in both paired and unpaired hepatocellular carcinoma samples compared to paracellular tissues." (PMID 38097352, 2023). "This combined clinical diagnostic utility of ENO1 and CA19-9 has also been reported previously for the detection of endometriosis, whereas ENO1 alone has been demonstrated to be a reliable diagnostic marker and independent prognostic marker for overall survival in hepatocellular carcinoma patients." (PMID 35204653, 2022). "Recent studies showed that ENO1 is upregulated in hepatocellular carcinoma (HCC) cells and has even higher expression in highly metastatic HCC cells as well as in exosomes." (PMID 34263260, 2021). "For instance, in hepatocellular carcinoma (HCC) cells, circRPN2 binds enolase 1 (ENO1) and accelerated ENO1 degradation, thereby regulating cell glycolysis." (PMID 38187401, 2023). "In contrast, hypoxia and HIF-1α induced expression of ENO1 and LDHA in another human cancer cell line, HEP3B hepatoma cells." (PMID 23866118, 2013). "Alpha-enolase (ENO1) has been found to be dysregulated in several human malignancies, including hepatocellular carcinoma (HCC)." (PMID 33184263, 2020). "It is quite a coincidence that circRPN2 could bind to ENO1 and accelerates its degradation to promote glycolytic reprogramming through the AKT/mTOR pathway, thereby inhibiting hepatocellular carcinoma (HCC) proliferation and metastasis." (PMID 36072431, 2022).
colorectal cancer (30 papers, 2014 to 2026). A primary or metastatic malignant neoplasm that affects the colon or rectum. "ENO1 was also reported to be associated with colorectal cancer." (PMID 32793472, 2020). "FBXW7 inhibits colorectal cancer by downregulating ENO1, reducing CCL20, lactate, proliferation, and migration." (PMID 41373479, 2025). "This increase in binding efficiency influenced the histone modification pattern of ENO1, resulting in increased glycolysis and tumorigenesis in colorectal cancer." (PMID 35924724, 2023). "Similar results were found in colorectal cancer where FBXW7 decreased tumor burden of colorectal carcinoma by negative regulation of enolase-1 (ENO1), NK2, mTOR, and PTEN." (PMID 37752997, 2023). "Zhan et al24 found that FBXW7, an E3 ligase, negatively regulates the expression of ENO1 by interacting with ENO1 and increasing its proteasomal degradation in colorectal cancer." (PMID 31957179, 2020). "Tumor intrinsic CD47 regulates glycolysis in colorectal cancer cells by stabilizing ENO1." (PMID 38390324, 2024). "In colorectal cancer, upregulation of enolase (ENO1) crotonylation promotes cell metastasis." (PMID 36949517, 2023). "Analysis of The Cancer Genome Atlas (TCGA) datasets revealed a positive correlation between MED15 expression and the expression of HIF target genes, including ENO1, HK2, and VEGFA, in renal and colorectal cancers." (PMID 39947475, 2025). "The findings demonstrated that enolase 1 (ENO1), modified by O-GlcNAcylation in colorectal cancer, simultaneously influences aerobic glycolysis and immune evasion." (PMID 41311582, 2025). "ENO1 has been previously found to promote tumorigenesis and metastasis via the AMPK/mTOR pathway in colorectal cancer." (PMID 29522283, 2018). "Furthermore, we used IHC to measure the expression levels of ENO1, GDF15, and H3K18la in subcutaneous colorectal cancer tumors from various treatment groups; the results were in line with earlier studies." (PMID 40775002, 2025). "In colorectal cancer, NSUN2 and YBX1 enhance ENO1 transcription via m5C RNA modification." (PMID 40843350, 2025). "The level of nonhistone ENO1-Kcr is elevated in colorectal cancer tissues, and ENO1K420Cr has been shown to stimulate the growth, migration and invasion of colorectal cancer cells in vitro." (PMID 38894712, 2024). "This study identifies NSUN2 and YBX1 as the m5C “writer” and “reader” of ENO1 in colorectal cancer, culminating in a positive feedback loop involving the NSUN2/YBX1/m5C‐ENO1 signaling axis, thereby bridging the connection between metabolic reprogramming and epigenetic remodeling." (PMID 38769664, 2024). "In colorectal cancer, the absence of EP300 inhibits the enzyme activity of ENO1 by reducing the level of lysine 2‐hydroxyisobutyrylation (Khib) on ENO1, thereby affecting glycolysis." (PMID 36999124, 2023).
glioblastoma (30 papers, 2012 to 2025). The most malignant astrocytic tumor (WHO grade IV). "ENO1 is located on chromosome 1p36.2 in an area harbouring numerous tumour suppressor genes and can become a ‘passenger’ deletion in glioblastomas and astrocytic tumours where loss of 1p36 is common." (PMID 38473245, 2024). "Among the common genes in both subpopulations, ENO1 was identified, a gene associated with metabolic and hypoxia processes known to promote cell growth, migration, and invasion in glioblastoma." (PMID 37958662, 2023). "The importance of this redundancy is highlighted by certain lineages of glioblastoma where the gene encoding ENO1 is collaterally deleted along with tumor suppressor genes during a translocation event." (PMID 31745118, 2019). "D423-Fluc glioblastoma tumor cells are deficient in glycolysis through deletion of enolase-1, which is on the 1p36 tumor suppressor locus, sensitizing them to mitochondrial metabolic blockers." (PMID 31766580, 2019). "This was demonstrated in glioblastoma when it was observed that inhibition of ENO2 was selectively toxic to ENO1 deficient glioblastoma cells." (PMID 26579514, 2015). "Loss of ENO1 sensitizes glioblastoma cells to ENO2 inhibition." (PMID 38638566, 2024). "This makes ENO2 a promising therapeutic target, and indeed, ENO2 inhibition by knockdown selectively suppressed the growth and tumorigenic potential of ENO1‐deleted glioblastoma cells." (PMID 40552664, 2025). "The glycolytic gene enolase 1 (ENO1), located on chromosome 1p36, is deleted in approximately 5% of glioblastoma patients, with ENO2 compensating for its loss." (PMID 40552664, 2025). "Panobinostat, romidepsin, and vorinostat can influence the Warburg effect by disrupting super-enhancers related to such genes as MYC, hexokinase 2 (HK2), GAPDH, and enolase 1 (ENO1) in glioblastoma models." (PMID 37190100, 2023). "Here, we further confirmed ENO1’s contributions to glioblastoma malignant behaviors via a series of rescue experiments, manifesting its critical role in glioblastoma progression." (PMID 36494582, 2023). "One of the genes utilized in the glycolytic score, ENO1, promoted M2 microglia polarization promoting immunosuppression and glioblastoma cell malignancy." (PMID 36900311, 2023). "The phosphonate-based HsENO2 inhibitors developed for treatment of ENO-1 deleted glioblastoma were tested against recombinant TbENO as a first step toward using them as potential leads against African trypanosomes." (PMID 38003754, 2023). "We finally confirmed that ENO1, the key gene of the GS, promoted M2 microglia polarization and glioblastoma cell malignant behaviors via immunofluorescence, clone formation, CCK8, and transwell rescue experiments." (PMID 36494582, 2023). "The function rescue results confirmed that ENO1 was engaged in promoting glioblastoma growth and migration." (PMID 36494582, 2023). "In a recent study, the enolase 1 gene (ENO1) has been identified as the potential target of curcumin in its antitumor effect against glioblastoma." (PMID 36307808, 2022). "By suppressing ENO1, curcumin inhibits glycolysis, which weakens the energy supply to glioblastoma cells and prevents their proliferation, invasion, and migration." (PMID 36307808, 2022). "In glioblastoma cell lines where an ENO1 deletion has occurred, the reaction in the glycolysis pathway is catalyzed by ENO2." (PMID 35628385, 2022). "The glycolytic gene ENO1 in the 1p36 locus is deleted in approximately 5% of glioblastoma patients, which is compensated by expression of ENO2." (PMID 33401771, 2021). "ENO1 is located on 1p36 and is responsible for the vast majority of enolase activity in glioblastoma." (PMID 32115576, 2020). "This upholds its role as a suitable analogue for examining the role of chirality in active site Enolase inhibition, especially for its use as an anticancer agent against ENO1-deleted glioblastoma." (PMID 31324042, 2019).
glioblastoma (continued). "The glycolytic enzyme ENO1 is essential for energy generation and anabolic processes in glioblastomas." (PMID 31798634, 2019). "Our previous work showed that SF2312 is a high potency Enolase inhibitor with potential utility for the treatment of glioblastoma with ENO1 deletions." (PMID 31324042, 2019). "Proof of principle has been demonstrated in glioblastoma where ENO1, a passenger gene frequently homozygously deleted at 1p36, leads to a synthetic vulnerability, whereby inhibition its paralogue, ENO2, in ENO1‐deficient cells is cell lethal." (PMID 28097822, 2017). "This has been observed in glioblastoma which have the glycolytic gene enolase 1 (ENO1) gene deleted as it is in the neighborhood of the 1p36 tumour-suppressor locus." (PMID 23006971, 2012). "ENO1 is a recurrently deleted passenger gene in glioblastoma." (PMID 38638566, 2024). "ENO1 serves as a relevant marker of glioblastoma aggressiveness and poor prognosis." (PMID 37958662, 2023). "These demonstrated that ENO1 in glioblastomas contributed to macrophage M2 polarization." (PMID 36494582, 2023). "Additionally, lincRNA SNHG18 has been shown to inhibit nuclear-cytoplasmic transport in glioblastoma cells by directly binding to α-enolase ENO1, thereby promoting glioblastoma cell invasion and migration." (PMID 37833349, 2023). "Using the collateral lethality paradigm, we previously reported that a subset of glioblastoma tumors with collateral homozygous deletion of ENO1 along with the 1p36 tumor suppressor locus is extraordinarily sensitive to the inhibition of ENO1’s redundant paralog ENO2." (PMID 34172075, 2021). "Therefore, ENO2 inhibition selectively suppresses the growth, survival, and tumorigenic potential of ENO1-deleted glioblastoma cells." (PMID 33401771, 2021). "Moreover, high expression of ENO1 was correlated with lower overall survival in glioblastomas." (PMID 37958662, 2023). "As an example, ENO1 is a gene that is homozygously deleted in glioblastoma (GBM) as a result of deletion in the 1p36 tumour-suppressor locus." (PMID 27686855, 2016). "Although ENO1 overexpression in GBM is correlated with a poor prognosis and drives malignant progression, its extracellular roles in glioblastoma remain notably unexplored." (PMID 41353343, 2025). "Collectively, our findings demonstrate that TMZ-induced autophagy-dependent ENO1 secretion activates two pivotal signaling axes, TLR4-mediated PI3K/Akt and SPHK1/S1P pathways, to drive glioblastoma malignancy." (PMID 41353343, 2025). "ENO1 has been reported to regulate the kinase activity of ERK1/2 in A549 cells, and ERK1/2 can modulate the nuclear translocation of PKM in U251 human glioblastoma cells that is necessary for PKM’s auto-regulation of expression." (PMID 28969663, 2017).
lung adenocarcinoma (29 papers, 2019 to 2025). A carcinoma that arises from the lung and is characterized by the presence of malignant glandular epithelial cells. "The researchers found that circ-ENO1 and its host gene ENO1 were up-regulated in lung adenocarcinoma (LUAD) cells." (PMID 40296917, 2025). "Circ-ENO1 upregulates the expression of ENO1 by adsorbing miR-22-3p, thus, promotes glycolysis of lung adenocarcinoma cells and tumour progression." (PMID 37599427, 2023). "For instance, circRNA-ENO1 elevates ENO1 expression to enhance glycolysis and tumor progression in lung adenocarcinoma." (PMID 36800233, 2023). "The up-regulation of METTL3 and down-regulation of ALKBH5 increased the overall m6A level and ENO1 mRNA methylation level in lung adenocarcinoma." (PMID 37582735, 2023). "A pan-cancer study showed that ENO1 was negatively correlated with B cells and macrophages in cervical carcinoma and B cells in lung adenocarcinoma." (PMID 36494582, 2023). "In lung adenocarcinoma, circ-ENO1 up-regulates the expression of ENO1 gene by interacting with miR-22-3p, resulting in an increase in ATP level, glucose uptake and lactate production of tumor cells, and promoting tumor proliferation." (PMID 37582735, 2023). "Circ-ENO1, also acting as a ceRNA, interacted with miR-22-3p to upregulate the expression of its host gene ENO1, and promoted glycolysis and tumor progression in lung adenocarcinoma (LUAD)." (PMID 37060016, 2023). "The combination of YTHDF1, a m6A “reader”, with methylated ENO1 mRNA leads to increased expression of ENO1 and promotes glycolysis of lung adenocarcinoma." (PMID 37582735, 2023). "Our data demonstrated that CCDC65 is a potential tumor suppressor by recruiting FBWX7 to suppress c-Myc/ENO1-induced cell cycle signal in lung adenocarcinoma." (PMID 35844805, 2022). "CircRNA Enolase 1 (ENO1) regulating the miR-22-3p/eNO1 axis accelerates glycolysis and tumor progression of lung adenocarcinoma." (PMID 34753394, 2022). "Our data demonstrated that CCDC65 was a potential tumor suppressor by recruiting FBWX7 to suppress c-Myc/ENO1-induced cell cycle signal in lung adenocarcinoma." (PMID 35844805, 2022). "CircRNA-ENO1 elevates the expression of its host gene ENO1 to promote glycolysis and tumor progression in lung adenocarcinoma through sequestering miR-22-3p35." (PMID 34420031, 2021). "Meanwhile, TCGA datasets revealed that ENO1 expression was significantly upregulated in lung adenocarcinoma and lung squamous carcinoma tissues compared to normal tissues." (PMID 34627260, 2021). "Mechanistically, circ-ENO1 acts as a ceRNA of miR-22-3p and upregulates ENO1 expression, promoting glycolysis and tumor progression in lung adenocarcinoma." (PMID 33634138, 2021). "The results demonstrated that circ-ENO1 acted as a ceRNA to interact with miR-22-3p and upregulate ENO1 expression, which promoted glycolysis and tumor progression in lung adenocarcinoma." (PMID 34489401, 2021). "Furthermore, recent research proved that upregulation of Circ-ENO1, and its host gene ENO1, correlate to tumorigenesis in lung adenocarcinoma (LUAD) cells." (PMID 35434271, 2022). "Additionally, another research shown that circ-ENO1 and its host gene ENO1 are increased in lung adenocarcinoma, promoting the glycolysis process and affecting tumor development and metastasis through the miR-22-3p/ENO1 axis." (PMID 35814779, 2022). "Furthermore, by regulating the miR-22-3p-ENO1 axis, circ-ENO1 has been shown to promote glycolysis and the development of lung adenocarcinoma." (PMID 36276846, 2022). "For example, circRNA‐ENO1 up‐regulated ENO1 expression to promote lung adenocarcinoma progression." (PMID 33237585, 2021). "Recently, circ-ENO1 and its host gene ENO1 are reported to be upregulated in lung adenocarcinoma." (PMID 33634138, 2021).